CAPN1 (calpain 1)
Diseases named in the same sentence as CAPN1 in open-access papers (continued):
Sharing a sentence is not in itself a finding about the gene and the disease.
atherosclerosis (4 papers, 2008 to 2023). A disease characterized by the build-up of fatty material and calcium deposition in the arterial wall resulting in partial or complete occlusion of the arterial lumen. "Therefore, targeting calpain-1 has the potential to delay or reverse the arterial remodeling that underlies age-associated diseases i.e. atherosclerosis." (PMID 18493299, 2008). "Thus, targeting calpain-1 is a potential approach to delay or reverse the age-associated arterial remodeling that is also associated with diseases such as hypertension, atherosclerosis, and stroke." (PMID 18493299, 2008). "Capn1/2 and Mep1a activation has been identified as a key driver of inflammation in other diseases of inflammation and remodeling, such as atherosclerosis and cardiac disease." (PMID 37340062, 2023).
Cognitive impairment (4 papers, 2020 to 2025). Abnormal cognition is characterized by deficits in thinking, reasoning, or remembering. "Other signs are rarer, but some cases with cognitive impairment and/or depression indicate that these signs should be assessed specifically in the follow-up of spastic ataxia with CAPN1 causative variants." (PMID 33486633, 2021). "Thus, the data support the hypothesis that calpain-1 and CaMKII activity modulation by UB-ALT-EV treatment might improve cell signaling and finally lead to reduced cognitive deficits presented by 5XFAD mice." (PMID 35810220, 2022).
glomerulosclerosis (4 papers, 2020 to 2025). A hardening of the kidney glomerulus caused by scarring of the blood vessels. "Calpain 1 and Calpain 2 activities are closely linked to both renal inflammatory response and aging, and suppression of Calpain 1 and 2 has been shown to relieve glomerulosclerosis and proteinuria." (PMID 35155498, 2022). "Treatment with calpain inhibitor III specifically inhibited calpain-1/-2 activities, mitigated the degree of proteinuria and glomerulosclerosis, and led to a striking increase in survival in the Gak-KO mice." (PMID 33208557, 2020). "Podocyte-specific deletion of Capns1, essential for calpain-1 and calpain-2 activities, also improved proteinuria and glomerulosclerosis in Gak-KO mice." (PMID 33208557, 2020).
ischemic stroke (4 papers, 2022 to 2024). A stroke disorder caused by obstruction of blood flow to the brain, due to thrombotic (local blood clot formation) or embolic (due to a blood clot or other material traveling from another site) event. "Calpain-1 and caspase-3 were positively correlated in ischemic stroke, suggesting that down-regulating calpain-1 inhibited apoptosis." (PMID 36569944, 2022). "Akin to the fragments generated by calpain-1 cleavage of pT286-rCaMKIIα in vitro, N-terminal fragments of CaMKIIα with molecular masses similar to ΔCaMKIIα-short (∼31 kDa) and ΔCaMKIIα-long (∼36 kDa) were detectable in brain cortex of mice subjected to ischemic stroke treatment." (PMID 37030595, 2023). "Interestingly, in acute MI and ischemic stroke, the expression of APAF1 and IRAK3 was negatively correlated with the abundance of NK cells, while the expression of ATM, CAPN1, IL1B, IL1R1, PRKACA, PRKACB and TNFRSF1A was positively correlated with the abundance of NK cells in MI." (PMID 38526027, 2024). "Interestingly, APAF1 and IRAK3 expression correlated negatively with NK cell abundance in both acute myocardial infarction and ischemic stroke, whereas ATM, CAPN1, IL1B, IL1R1, PRKACA, PRKACB, and TNFRSF1A correlated negatively with NK cell abundance in acute myocardial infarction." (PMID 35432334, 2022).
ovarian carcinoma (4 papers, 2012 to 2024). A malignant neoplasm originating from the surface ovarian epithelium. "No prior studies have investigated the expression of calpastatin, calpain-1 and calpain-2 in ovarian cancer, or have tested their association with response to platinum-based chemotherapy in tissue samples." (PMID 22435971, 2012). "MAP4, Syk, and calpain-1 are interrelated and interact to regulate ovarian cancer cell proliferation." (PMID 38341398, 2024). "Calpain-1, calpain-2, calpain-4 and calpastatin expression were evaluated in primary ovarian carcinomas (n = 575) by immunohistochemistry." (PMID 30448882, 2019). "Tissue expression of calpastatin, calpain-1 and calpain-2 was assessed in a series of 154 ovarian cancer patients treated with platinum-based chemotherapy." (PMID 22435971, 2012). "The expression of calpain-1, calpain-2 and calpastatin were determined using standard immunohistochemistry on a tissue microarray of 154 primary ovarian carcinomas from patients subsequently treated with platinum-based adjuvant chemotherapy." (PMID 22435971, 2012). "The expression levels of calpastatin, calpain-1 and calpain-2 were determined in a cohort of 154 ovarian cancer patients treated with platinum-based adjuvant chemotherapy." (PMID 22435971, 2012). "Calpain-1 showed a significant association with organ-confined ovarian cancers rather than cancers with distant metastases, with low calpain-1 more frequent in organ-confined ovarian cancers (χ2 = 11.310, df = 1, P = 0.001)." (PMID 30448882, 2019).
pancreatic cancer (4 papers, 2012 to 2022). "CAPN1 was overexpressed in pancreatic cancer (PC) tissues and cells and associated with tumor site, metastasis, TNM stage and overall survival of PC patients." (PMID 32395869, 2020). "When calpain-1 expression in pancreatic cancer cells was downregulated by siRNA in AsPC-1 and BxPC-3 cell lines, the invasion and migration abilities of pancreatic cancer cells were significantly attenuated." (PMID 33430230, 2021). "This study examined the expression of calpain-1 (μ-calpain catalytic subunit), calpain-2 (m-calpain subunit) and calpastatin in cancers of the pancreas, bile duct and ampulla using immunohistochemistry." (PMID 23140395, 2012).
spastic ataxia (4 papers, 2019 to 2022). "CAPN1 variants were initially associated with an autosomal recessive (AR) form of complex HSP (SPG76) or spastic ataxia in 2016." (PMID 33486633, 2021). "We diagnosed a series of 21 cases of spastic ataxia with CAPN1 causative variants from 13 new families." (PMID 33486633, 2021). "CAPN1 disease-causing variants are a rare cause of spastic ataxia of young adult onset, often involving consanguineous families." (PMID 33486633, 2021). "We described a large series of 21 patients from 13 families with CAPN1 pathogenic variants causing various degrees of spastic ataxia, including nine novel variants." (PMID 33486633, 2021). "CAPN1 variants are a rare cause (~ 1.4%) of young-adult-onset spastic ataxia; however, together with all published cases, they allowed us to better describe the clinical and genetic spectra of this form." (PMID 33486633, 2021). "CAPN1 mutations were first linked to a spastic ataxia phenotype in 2016." (PMID 36247768, 2022). "The variant c.759 + 1G > A in CAPN1 was previously identified in a family with spastic ataxia." (PMID 31289639, 2019).
Stroke (4 papers, 2008 to 2023). Sudden impairment of blood flow to a part of the brain due to occlusion or rupture of an artery to the brain. "Mitochondrial ROS influence the release of cytochrome c and other apoptotic proteins (such as caspase-3, caspase-8, and calpain-1) from the mitochondria into the neuronal cytosol, which leads to apoptosis after stroke." (PMID 33656055, 2021). "MAPK has previously been implicated in the regulation of calpain activity, thus we sought to explore the intrinsic link between p38 MAPK and calpain 1 in our stroke recovery model." (PMID 27336717, 2016). "Our results suggested that p38 MAPK is a downstream signal molecule for IL-17 A to inhibit calpain 1 in our stroke recovery model." (PMID 27336717, 2016). "In addition, EE promotes functional recovery after stroke by inhibiting calpain 1 activity." (PMID 37688770, 2023).
Viral infection (4 papers, 2019 to 2025). "Calpain 1 is identified as a novel protein associated with viral infection that interacts with CD163 to facilitate PRRSV uncoating in the EE." (PMID 32038556, 2019). "Viral infection induces mitochondrial apoptosis in the myocardium and promotes the translocation of calpain-1, a cytosolic calcium-activated cysteine protease, into the mitochondria." (PMID 41179105, 2025). "Human CTSL and CAPN1 are important drug targets because they play key roles in viral entry into host cells and virus infection-mediated “cytokine storm”." (PMID 38443334, 2024). "Since an obvious effect of calpain 1 on virus replication was observed, we next determined how the protein participated in suppressing virus infection." (PMID 32038556, 2019). "However, calpeptin lost its inhibitory effect on PRRSV-N expression when added at a post-entry time point (added 2 hpi), indicating that the role of calpain 1 in viral infection is specific to early events of the infection." (PMID 32038556, 2019). "Therefore, dual inhibitors targeting host CTSL and CAPN1 might bring broad-spectrum synergistic efficacy to the fight against coronavirus in the future, while reducing excess inflammation to improve symptoms in patients with viral infections." (PMID 38443334, 2024).
Cerebral ischemia (3 papers, 2020 to 2023). Restriction of arterial blood supply to the brain associated with insufficient oxygenation to support the metabolic requirements of the tissue. "Oxytocin may also have a neuroprotective function in neurons against cerebral ischemia via the attenuation of calpain-1, which is implicated in the cell death process." (PMID 33379208, 2020). "Recently, very early treatment with zonisamide was shown to decrease morbidity by suppressing the expression of caspase-3, caspase-8, and calpain-1, inhibiting the apoptosis of neuronal cells after cerebral ischemia." (PMID 36824441, 2022).
depression (3 papers, 2020 to 2022). "In the CUMS model, PSP improved depression-like behaviors and inhibited the expression of calpain-1 and inflammation-related proteins." (PMID 35498131, 2022). "We previously showed that a calpain inhibitor and fluoxetine could both prevent LPS-induced depression-like behaviors but had different effects on calpain-1 expression." (PMID 35498131, 2022). "This pathway has also been proposed to participate in anxiety, depression and drug addiction, and it will be of interest to further explore potential phenotypic differences related to these behaviors in calpain-1 KO mice." (PMID 32328086, 2020).
glioblastoma (3 papers, 2022 to 2024). The most malignant astrocytic tumor (WHO grade IV). "Human surgical specimens also showed elevated CAPN1 expression by both immunohistochemistry and western blotting, indicating the potential of this probe for glioblastoma detection during the surgery in the future." (PMID 38516394, 2024). "In a recent study, calpain-1 activity was used to stain glioblastoma during surgical intervention leading to a spatial distinction between tumor and peritumoral tissue." (PMID 36932402, 2023). "The fluorescent probe proline–arginine–HMRG reacts with calpain-1, which is highly expressed in glioblastoma cell line U87, and can distinguish tumors from peritumoral tissues in vitro." (PMID 35600609, 2022). "In U87 glioblastoma cells, CAPN1 knockdown reduced PR-HMRG fluorescence." (PMID 38516394, 2024). "In the present study, we used patient samples of initial and recurrent glioblastoma as well as of non-malignant brain tissue to study the expression profiles of calpain-1 and calpain-2." (PMID 36932402, 2023).
heart failure (3 papers, 2021 to 2025). Inability of the heart to pump blood at an adequate rate to meet tissue metabolic requirements. "Calpains are a family of calcium-activated cysteine proteases, and calpain 1 (CAPN1) is the predominant isoform in cardiomyocytes, which are involved in signal transduction that leads to myocardial remodeling and heart failure." (PMID 40634996, 2025).
lung adenocarcinoma (3 papers, 2020 to 2022). A carcinoma that arises from the lung and is characterized by the presence of malignant glandular epithelial cells. "In summary, the current study demonstrated that the two genetic variants, CAPN1 rs17583C>T and LINC00959 rs4751162A>G, was associated with survival outcomes of patients with lung adenocarcinoma after surgical resection." (PMID 34728688, 2021). "We found that two genetic variants, CAPN1 rs17583C>T and LINC00959 rs4751162A>G, in the histone modification regions were associated with the survival outcomes of patients with lung adenocarcinoma who underwent curative surgery." (PMID 34728688, 2021). "Meanwhile, CAPN1 may be a biomarker of tumor or a potential target used to diagnose and treat lung adenocarcinoma." (PMID 36092153, 2022). "The CAPN1 expression was significantly higher in lung adenocarcinoma than normal lung." (PMID 34728688, 2021). "Our results suggest that CAPN1 and GLRX3 may play important roles in the pathogenesis of lung adenocarcinoma, and that the variants may be useful in predicting the prognosis of lung adenocarcinoma after surgery, thereby helping to refine therapeutic decisions for better clinical outcomes in NSCLC." (PMID 34728688, 2021). "This study aimed to reveal the effects of CAPN1/PTPN1 on malignant phenotype and EGFR‐TKI resistance of lung adenocarcinoma (LUAD) cells." (PMID 32395869, 2020). "Superior CAPN1 and inferior PTPN1 were related to activation of c‐Met/PIK3R2 in lung adenocarcinoma." (PMID 32395869, 2020).
myocardial ischemia (3 papers, 2022 to 2024). A disorder of cardiac function caused by insufficient blood flow to the muscle tissue of the heart. "Additionally, loss of CAPN1 reduces myocardial ischemia-reperfusion injury through the pyroptosis in mice." (PMID 35308143, 2022). "Calpain 1 activation is involved in different processes that occur in response to myocardial ischemia, including cytoskeletal remodeling, cell–cell adhesion disassembly, and cardiomyocyte death." (PMID 35883722, 2022). "In addition, the hERG/IKr channel was selectively cleaved by serine proteases, such as proteinase K (PK) in the S5-pore linker of the hERG, and calpain-1, which is upregulated in cardiac ischemia, and in the Gly-603 in the S5-pore linker of the hERG." (PMID 38732154, 2024).
myocarditis (3 papers, 2022 to 2024). Myocarditis is a condition that is characterized by inflammation of the heart muscle (myocardium). "Targeting NLRP3 inflammasome with calpain-1 inhibitor has been shown to control myocarditis progression; however, the benefit of calpain inhibition has not been demonstrated in a clinical trial." (PMID 35997820, 2022). "Our study provides new perspectives on the regulation of NLRP3 inflammasome in myocarditis and suggests that calpain-1 can affect not only the expression of NLRP3 but also the assembly of the inflammasome complex." (PMID 35997820, 2022). "To validate our findings in vivo and determine if calpain-1 was the dominant calpain in CVB3-induced myocarditis, we treated neonatal rat cardiomyocytes with the calpain-1 selective inhibitor PD151746 after CVB3 infection." (PMID 35997820, 2022). "Therefore, targeting the calpain-1 pathway is a novel therapeutic approach for repressing the activation of the NLRP3 inflammasome for the treatment of myocarditis and other inflammatory diseases." (PMID 35997820, 2022). "We investigated whether NOD-, LRR-, and pyrin domain-containing 3 (NLRP3) inflammasome participated in CVB3-induced myocarditis, and investigated the effects of calpain-1 on CVB3-induced cardiac injury." (PMID 35997820, 2022).
neuroblastoma (3 papers, 2014 to 2019). Neuroblastoma (NB) is the most common solid, extracranial childhood tumor. "We have previously demonstrated that in human neuroblastoma SKNBE cells calpain 1, together with its modulator HSP90, is constitutively associated to NR1/NR2B protein cluster." (PMID 26431040, 2015). "We are here reporting that in SKNBE neuroblastoma cells or in freshly isolated nerve terminals from adult rat hippocampus, the proteolytic activity of calpain 1 resident at the NMDAR is very low under basal conditions and greatly increases following NMDAR stimulation." (PMID 26431040, 2015). "Our data indicate that, in SKNBE neuroblastoma cells, the chaperone HSP90 plays a specific role in the control of the dynamic activation of calpain 1 and that the chaperone can assist the protease during its recruitment in the multiprotein NMDAR cluster." (PMID 26431040, 2015). "To assess the functional relevance of down-regulation of KLK6 level and CAPN1, we used SH-SY5Y neuroblastoma cells, within which there was partial co-localisation of KLK6 and CAPN1 with α-syn." (PMID 25476568, 2014). "Hence, we performed the therapeutic effect of LP17 on active caspase-3 in neuroblastoma, SH-SY5Y cell which could confirm its inhibition on calpain-1 in our preliminary study (data not shown)." (PMID 31440123, 2019).
Spastic paraplegia (3 papers, 2021). Complete loss of the ability to move the lower limbs accompanied by spasticity of the lower limbs. "Among them, CAPN1, when mutated, is responsible for a complex inherited form of spastic paraplegia (SPG76)." (PMID 33486633, 2021). "The proband also has compound heterozygous missense mutations in CAPN1, which may be resulting in an atypical version of the Mendelian disease spastic paraplegia-76 (SPG76), in particular since this subtype is associated with young adult spastic paraplegia onset." (PMID 33597717, 2021).
acute myocardial infarction (2 papers, 2017 to 2022). Necrosis of the myocardium, as a result of interruption of the blood supply to the area. "Furthermore, deletion of calpain-4, the common small subunit of calpain-1 and -2 in cardiomyocytes resulted in suppressed NF-kB activity followed myocardial infarction in mice." (PMID 29089532, 2017).
amyotrophic lateral sclerosis (2 papers, 2017 to 2021). Amyotrophic lateral sclerosis (ALS) is a neurodegenerative disease characterized by progressive muscular paralysis reflecting degeneration of motor neurons in the primary motor cortex, corticospinal tracts, brainstem and spinal cord. "In neurons, moderate calpain-1 activation (as we observe in IBM samples) causes cleavage of TDP-43 into aggregation-prone fragments, promoting the TDP-43 cytoplasmic mislocalization (TDP-43 proteinopathy) observed in amyotrophic lateral sclerosis." (PMID 28330496, 2017).
asthma (2 papers, 2022 to 2023). "The role of calpain 1 in lung parenchymal damage has also been described in other diseases such as pneumonia, chronic obstructive pulmonary disease, asthma, and lung damage associated with mechanical ventilation." (PMID 37509486, 2023). "Nineteen differentially expressed PRGs were included in the mild-to-moderate and severe asthma samples, among which CAPN1, NLRP1, TRIM31, NOS2, and CDC37 showed the highest difference (P<0.01)." (PMID 35967302, 2022).
Atrophy (2 papers, 2014 to 2022). Any weakening or degeneration, especially through lack of use. "In our cohort, muscle atrophy gene expressions of Atrogin-1 and Calpain-1 were more severely upregulated in female patients only in the group comparison by non-parametric tests." (PMID 35160299, 2022).
cardiomyopathies (2 papers, 2017 to 2024). "Furthermore, we show that breakdown of cardiac Erk5 by Gp91phox-dependent calpain-1 activity underlies the pathological mechanism of metabolic stress-induced cardiomyopathy." (PMID 28887535, 2017). "Four variants, c.302G>C/p.Gly101Ala (CAPN1), c.637C>T/p.Arg213Trp (MTUS2), c.457C>T/p.Arg153Cys (CRTAC1), c.1309G>T/p.Gly437Cys (UNC45A), were associated with cardiomyopathies." (PMID 38848015, 2024). "Here the authors show that high fat diet causes calpain-1-dependent degradation of ERK5 leading to mitochondrial dysfunction, suggesting the maintenance of cardiac ERK5 as a therapeutic approach for cardiomyopathy prevention and/or treatment." (PMID 28887535, 2017).